MIR6852 (microRNA 6852)
Synonyms: hsa-mir-6852
Gene: MicroRNA gene on chromosome 9 (35,710,676 to 35,710,741, reverse strand). Ensembl gene ENSG00000284195.
Homologues: Orthologues: chimpanzee MIR6852 (100% identical).
Diseases named in the same sentence as MIR6852 in open-access papers:
MIR6852 is named in the same sentence as 1 disease in open-access papers, as found by Europe PMC text mining. Sharing a sentence is not in itself a finding about the gene and the disease. The quoted sentences say what the papers report.
lung carcinoma (2 papers, 2019 to 2025). "To uncover the physiological role of MIR6852 in lung cancer, we first examined the expression levels of MIR6852 in ADC cell lines." (PMID 30787392, 2019).